RBFOX2 (RNA binding fox-1 homolog 2)
Diseases named in the same sentence as RBFOX2 in open-access papers (continued):
Sharing a sentence is not in itself a finding about the gene and the disease.
cancer (39 papers, 2008 to 2025). A tumor composed of atypical neoplastic, often pleomorphic cells that invade other tissues. "Dysregulation of RBFOX2‐mediated alternative splicing has been closely linked to a spectrum of cardiovascular diseases and malignant tumours, underscoring its potential as a therapeutic target." (PMID 39243148, 2024). "RBFOX2 is essential for human ES cell survival 26 and is associated with developmental fates 14 and cancer progression." (PMID 38114498, 2023). "Here we demonstrated that Rbfox2 migrates to the cytoplasm in response to external stress and modulates the expression of target mRNAs associated with cancer development, thereby affecting cancer progression." (PMID 31028247, 2019). "Nevertheless, these results further support the association between QKI and RBFOX2 and alternative splicing in the indicated cancers." (PMID 25908786, 2015). "RBFOX2 has emerged as a diagnostic marker in cancer and a potential therapeutic target." (PMID 39243148, 2024). "Notably, RBFOX2 expression exhibited a positive association with a wide range of chemokine-related genes and genes related to chemokine receptors in the majority of cancer cases." (PMID 38881877, 2024). "RBFOX2 has been linked to a proepithelial to EMT phenotype in several cancer types." (PMID 35127712, 2021). "Therefore, in this study, we confirmed that Rbfox2 dissociation from RB1 mRNA associated with SGs following resveratrol treatment inhibited cancer progression." (PMID 31028247, 2019). "However, recent studies have shown an association between RBFOX2 functions and cancer progression." (PMID 39375538, 2024). "We have expanded upon the knowledge in the field by demonstrating that the overlapping action of QKI and RBFOX2 is not limited to cancer but is also an active regulatory mechanism in muscle." (PMID 40207498, 2025). "The investigation made use of both the DNMIVD and CPTAC datasets to examine the methylation status of RBFOX2 in diverse cancer types." (PMID 38881877, 2024). "The findings showed that RBFOX2 was linked to CD8+ T cells, CAFs, and Tregs in different types of cancer." (PMID 38881877, 2024). "We observed differential expression of RBFOX2 in pan-cancer, indicating its significant and crucial role in tumor development." (PMID 38881877, 2024). "We summarized the expression of RBFOX2 and its correlation with OS in pan-cancer and found that higher RBFOX2 in HNSC, PAAD, STAD and THYM was consistent with its poor indicator for OS.." (PMID 38881877, 2024). "In CRC cells (HCT116), RBFOX2 directly binds to ARHGEF7 pre‐mRNA, promoting the inclusion of cancer‐associated micro‐exons and promoting tumour invasion and migration." (PMID 39243148, 2024). "Future exploration of PTMs and RBFOX2 isoforms promises a comprehensive understanding of its role in cancer and other diseases." (PMID 39243148, 2024). "It is important to note that RBFOX2 predominantly localises within the nucleus, although its cytoplasmic localisation appears to be cancer cell‐specific." (PMID 39243148, 2024). "The results demonstrated a significant association between RBFOX2 expression and essential aspects of the TME, such as immune score, stromal score, and tumor purity across multiple cancer types." (PMID 38881877, 2024). "Within the realm of cancer, RBFOX2 emerges as a potential biomarker, wielded for both diagnostic and prognostic purposes, while its aberrant expression forms an intricate association with the extent of tumour malignancy." (PMID 39243148, 2024). "Among RBPs, the RBFOX family, particularly RBFOX2, plays a crucial role in alternative RNA splicing, impacting diseases such as cancer and heart disease." (PMID 39243148, 2024). "To conclude, we conducted an investigation on the expression of RBFOX2 in different types of cancer and its correlation with patient prognosis." (PMID 38881877, 2024). "In the context of cancer, RBFOX2 undergoes dysregulation at various levels within cells and tissues." (PMID 39243148, 2024).
cancer (continued). "In this investigation, we examined the expression of RBFOX2 across various cancers using the TCGA and CCLE database." (PMID 38881877, 2024). "Functional enrichment analysis was further performed to study the biological value and signaling pathways of RBFOX2 expression in various cancers." (PMID 38881877, 2024). "Our study focused on RBFOX2 since it is among the most studied alternative splicing factors implicated in the development of EMT, cancer progression, and metastatic process." (PMID 39098911, 2024). "Overall, the data in the literature attributed to RBFOX2 a role as an inductor of oncogenic splice-switching that drives an invasive phenotype in cancer." (PMID 39098911, 2024). "For example, CD47, a receptor widely expressed in cancer cells facilitating evasion from immune system phagocytosis, experiences downregulation of splice isoforms through RBFOX2 in paediatric AML‐derived HSCs/HPCs, subsequently impeding tumour proliferation." (PMID 39243148, 2024). "These insights illuminate the intricate regulatory roles of RBFOX2 in different cancer contexts, providing valuable clues for targeted therapeutic interventions." (PMID 39243148, 2024). "Given the evidence for conserved exon splicing events in cancer and our limited understanding of these events in PDAC, we further characterized the differential exon splicing events associated with RBFOX2 in our pancreas cell line and tumor models." (PMID 38114498, 2023). "The human homologs of the top three RNA binding proteins identified in our screen, MBNL2, MBNL1 and RBFOX2, are differentially regulated in cancer transcriptionally and post-transcriptionally through alternative splicing." (PMID 38114498, 2023). "Defining mechanisms regulating RBFOX2 splicing function in cancer will be critical to further our understanding of the context dependency of the RBFOX2 splicing program driving metastasis in PDAC." (PMID 38114498, 2023). "In fact, RBFOX2 is involved in alternative splicing in mesenchymal tissues and during the epithelial-mesenchymal transition process, which is important for cancer cell metastasis." (PMID 36707502, 2023). "Thereby suggesting that targeting FKBP2_AP to regulate the expression of RBFOX2 to control its alternative splicing events as potential diagnostic and therapeutic targets for HCV-related cancers is of benefit." (PMID 33530521, 2021). "Remarkably, by isolating Rbfox2 from the structure of SGs, resveratrol inhibited its effect on Rb1 and effectively reduced the proliferation of cancer cells." (PMID 34604242, 2021). "The RNA-binding Fox protein 2 (Rbfox2) is downregulated in many forms of cancer where it upregulates tumor suppressor miRNAs." (PMID 34944633, 2021). "RBFOX2 promotes tumor progression by acting as a splicer of EMT-related genes in several types of cancers; however, the status and role of RBFOX2 in GC is unclear." (PMID 35127712, 2021). "The results suggest that the subcellular localization of Rbfox2 to the cytoplasm is cancer cell-specific." (PMID 31028247, 2019). "Rbfox2 is involved in mesenchymal tissue-specific splicing during the epithelial-mesenchymal transition, which is important for cancer cell metastasis." (PMID 31028247, 2019). "Resveratrol, an antioxidant found in red grapes, slows cancer progression by interfering with the localization and function of the RNA-binding protein Rbfox2." (PMID 31028247, 2019). "We confirmed that Rbfox2 expression in cancer tissue was significantly elevated relative to that in normal tissue, whereas RB1 expression was markedly decreased in cancer tissue compared to normal tissue." (PMID 31028247, 2019). "For example, RBFOX2 is downregulated in ovary and breast cancers, and dictates many changes in the alternative splicing pattern of these cancers." (PMID 25908786, 2015). "Rbfox2 has been shown to be critical in regulating cancer subtype specific alternative splicing programs and in mediating EMT specific splicing programs." (PMID 23484019, 2013).
cancer (continued). "Our discoveries propose the potential utilization of RBFOX2 as a predictive marker, emphasizing its pivotal involvement in the tumor microenvironment across various malignancies, thereby underscoring its potential influence on cancer immunotherapy." (PMID 38881877, 2024). "In various other cancer types, RBFOX2 has displayed similar tumour‐promoting functions." (PMID 39243148, 2024). "However, further research is needed to validate the potential role of RBFOX2 methylation in these cancers." (PMID 38881877, 2024). "Our results suggest that variations in promoter methylation levels might contribute to the differential expression of RBFOX2 in pan-cancer." (PMID 38881877, 2024). "In CRC, RBFOX2 registers upregulation in cancer tissues compared to normal counterparts." (PMID 39243148, 2024). "Notably, NEK2, a cancer‐associated factor linked to tumour progression and treatment resistance, promotes the premesenchymal splicing pattern of TNBC cells by upregulating RBFOX2 expression." (PMID 39243148, 2024). "Overall, these results suggested that RBFOX2 may influence the development of pan-cancer by actively participating in and interacting with the TME." (PMID 38881877, 2024). "Furthermore, we specifically focused on exploring the interplay among DNA methylation, RBFOX2 expression and prognosis in pan-cancer." (PMID 38881877, 2024). "RBFOX2, with its multifaceted role in alternative splicing, emerges as a crucial player in the pathogenesis of CVDs, cancers and other disorders, notably contributing to treatment resistance in malignant tumours." (PMID 39243148, 2024). "Aberrant RBFOX2 expression serves as a valuable biomarker for assessing the malignancy of cancer." (PMID 39243148, 2024). "Therefore, we conducted an analysis on the correlation between DNA methylation and the expression of RBFOX2 in various types of cancers." (PMID 38881877, 2024). "Furthermore, RBFOX2 expression showed a significant association with immunosuppressive genes like PD-L1, CTLA4, VTCN1, KDR, and TGFBR1 across different types of cancers." (PMID 38881877, 2024). "Notably, RBFOX2 plays a critical role in bolstering the viability of cancer cells even following treatment, thereby constituting a substantial contributing factor to the development of tumour resistance against anticancer therapies." (PMID 39243148, 2024). "Dysregulated RNA‐binding fox‐1 homologue 2 (RBFOX2) in cancers." (PMID 39243148, 2024). "For instance, RBFOX2 was recently identified as a central splicing factor in the differential splicing network, and it is commonly featured in numerous splicing events related to cancer." (PMID 33530521, 2021). "Rbfox2 in the structure of SGs affecting the mRNA of Rb1, a tumor suppressor, and reducing its stability and expression, increases the proliferation process in cancer cells." (PMID 34604242, 2021). "Notably, the significant association of RBFOX2 and HOXA is a common feature among cancers generated from different tissues." (PMID 32883226, 2020). "Similarly, in a mouse primary tumor model, Rbfox2 localization and cancer proliferation were inhibited by resveratrol administration." (PMID 31028247, 2019). "Furthermore, the in vivo mouse model demonstrated that resveratrol administration inhibited Rbfox2 localization to the cytoplasm and inhibited cancer progression." (PMID 31028247, 2019). "Consequently, targeting RBFOX2 holds significant promise as a cancer therapy." (PMID 39243148, 2024). "Moreover, although RBFOX2 is known to regulate some of these genes, the role of RBFOX2-mediated splicing events on signaling pathways in cancer remains largely unknown." (PMID 37296107, 2023). "Since abnormal cells, including cancer cells, are under various cellular stresses such as oxidative stress, nutrient stress, and osmotic stress, we speculate that regulation of the RB1-mediated cell cycle by Rbfox2 could play a role in disease development and cancer progression." (PMID 28894257, 2017).
cancer (continued). "Among these 17 “RNA-binding” genes, RBFOX2 and NOVA1 have been reported to be essential for maintaining cancer stemness and are known for their roles in the EMT." (PMID 39420119, 2024). "RBFOX2, a well-characterized regulator of alternative splicing, has been reported involved in EMT and contributes to metastasis of several cancers." (PMID 38881877, 2024). "This research aimed to explore the correlation between RBFOX2 expression and OS, DSS, DFI, and PFI in a wide range of cancers." (PMID 38881877, 2024). "This interaction prevents RBFOX2 from binding to TFRC pre‐mRNA, showcasing the intricate regulatory network governing RNA splicing in cancer cells." (PMID 39243148, 2024). "RBFOX2 is a regulator of alternative splicing involved in the EMT process and contributes to the increased invasiveness of cancer cells that have undergone EMT." (PMID 35127712, 2021). "RBFOX2 was also shown to be a major regulator of EMT and to promote the mesenchymal splicing pattern of several cancer-relevant genes." (PMID 34930366, 2021). "MBNL1/2, RBFOX2 and QKI were downregulated in most of the cancer types and, as expected, their motifs were enriched in these cancer types upstream to exons with higher exclusion and downstream to exons with higher inclusion in cancer." (PMID 25908786, 2015). "Specific splicing regulators, including RBFOX2, MBNL1/2 and QKI, appear to account for many splicing alteration events in multiple cancer types." (PMID 25908786, 2015). "We show that many of these events are shared among different cancer types; our data also suggest that specific splicing factors, namely RBFOX2, QKI, MBNL1/2, PTBP1 and CELF2 are probably responsible for many of the alterations detected in these cancer types." (PMID 25908786, 2015). "Furthermore, RBFOX2 affects the expression of Hippo-YAP pathway by regulating the splicing of TEAD1 exon 6, thereby increasing the oncogenic properties of cancer." (PMID 38881877, 2024). "Our analysis revealed a strong negative correlation between PBRM1 E27 PSI and RBFOX2 expression in most cancer types." (PMID 39375538, 2024). "However, the unclearness pertaining to the expression of RBFOX2, its prognostic potential, and its correlation with the tumor microenvironment (TME) in pan-cancer persists." (PMID 38881877, 2024). "Actually, RBFOX2 shows positive correlation with Treg in majority of cancer types in QUANTISEQ, while shows negative correlation with Treg in some cancer types in CIBERSORT." (PMID 38881877, 2024). "While there have been prior investigations emphasizing the significance of RBFOX2 in the context of cancer, a holistic evaluation encompassing multiple cancer types is still lacking." (PMID 38881877, 2024). "Indeed, in addition to muscle cells, RBFox2 is ubiquitously expressed with high abundance in most cell types, including MEF, fibroblasts, embryonic stem cells, and cancer cells." (PMID 36674797, 2023). "Rbfox2 in the structure of SGs promotes cell proliferation by influencing and decreasing RB1 expression.Resveratrol inhibits Rbfox2 activity on RB1 and decreases cancer expansion by separating Rbfox2 from the structure of SGs." (PMID 35004322, 2021). "RBP fox-1 homolog 2 (Rbfox2), a component of SGs, binds to retinoblastoma 1 (RB1) mRNA, which is closely related to cancer progression; however, the role of Rbfox2 in cancer progression remains largely unknown." (PMID 31028247, 2019). "Moreover, Rbfox2 reduced RB1 protein levels under stress conditions and promoted cancer cell cycle progression and proliferation." (PMID 31028247, 2019).
tumor (28 papers, 2010 to 2026). "Our results show that most of the genes are negatively correlated with these drugs (based on IC50 values) between high- and low-risk groups in each tumor except for RBFOX2 in some tumors, YTHDF1 in SKCM and LUAD, FTO in LUSC and TGCT, and FMR1 in OV and UCS." (PMID 39457524, 2024). "Analysis of messenger RNA splicing in a large cohort of pancreatic ductal adenocarcinoma tumours identifies differential splicing correlating with disease progression, associated with the the splicing regulator RBFOX2." (PMID 36949200, 2023). "In this study, we showed RBFOX2 is an important regulator of alternative splicing in PDAC and that loss of nuclear RBFOX2 promoted increased tumor growth and metastasis in vivo." (PMID 38114498, 2023). "However, the promoter methylation was lower in tumor tissues, and a lower promoter methylation of RBFOX2 was associated with worse OS for BRCA patients." (PMID 38881877, 2024). "TIA1 and RBFOX2 were reportedly associated with tumor relapse or metastasis in malignancies." (PMID 36147313, 2022). "In hepatocellular carcinoma, the HIF-1α/METTL16/lnc-CSMD1-7/RBFOX2 signaling axis has been shown to regulate interactions between tumor cells and the tumor microenvironment, particularly influencing cell behaviors such as epithelial–mesenchymal transition." (PMID 41459114, 2026). "In this study, IHC experiments revealed that RBFOX2 expression was lower in tumor tissues compared to paired adjacent tissues." (PMID 38881877, 2024). "Specifically, we observed lower RBFOX2 levels in tumor tissues of HCC patients in comparison to neighboring tissues." (PMID 38881877, 2024). "In contrast to these findings, some studies reveal that RBFOX2 can also exert inhibitory effects on tumour proliferation and invasion." (PMID 39243148, 2024). "On the other hand, in KIRC, both RBFOX2 gene expression and promoter methylation were higher in tumor tissues, suggesting the involvement of other mechanisms in increasing the expression level of RBFOX2." (PMID 38881877, 2024). "These collective results suggested that higher RBFOX2 expression equivalent to a protective role in most tumor types." (PMID 38881877, 2024). "Our findings indicate that RBFOX2 methylation is closely linked to OS, DSS and PFS in certain tumor patients." (PMID 38881877, 2024). "Further, RBFOX2 depletion promotes tumor growth and metastasis to the liver and mesentery in orthotopic mouse models." (PMID 38114498, 2023). "The half-life of RBFOX2 mRNA is similar in the metastatic and in the primary tumour cell lines, whereas the half-life of RBFOX2 protein is shorter in the metastatic X50 cells, suggesting enhanced protein degradation." (PMID 36949200, 2023). "Expression of RBFOX2ΔRRM did not attenuate the phenotype in either cell line, suggesting that the RRM of RBFOX2 is essential for its tumour suppressor activity in PDA progression." (PMID 36949200, 2023). "Further, we showed that RBFOX2 depletion in a murine cell line derived from the KPC PDAC GEMM promotes PDAC tumor growth in a C57BL/6 J immune competent orthotopic model." (PMID 38114498, 2023). "Using TMAs from resected patient samples, we found RBFOX2 abundance and cellular distribution is heterogeneous within tumor cores and is enriched in acinar cells and early neoplastic lesions within adenocarcinoma." (PMID 38114498, 2023). "These pathways are well-known regulators of the actin cytoskeleton, cell polarity, microtubule dynamics and vesicle trafficking, supporting a biological role for RBFOX2 as a metastatic tumour suppressor in PDA." (PMID 36949200, 2023). "Our results implicate the splicing-regulatory function of RBFOX2 as a tumour suppressor in PDA and suggest a therapeutic approach for metastatic PDA." (PMID 36949200, 2023).